S100A9 (S100 calcium binding protein A9)
Diseases named in the same sentence as S100A9 in open-access papers (continued):
Sharing a sentence is not in itself a finding about the gene and the disease.
colon adenocarcinoma (3 papers, 2017 to 2025). "Immunohistochemical results showed that β-catenin, c-Myc, p-Akt, and Cxcl5 were strongly upregulated in CAC mice colon adenocarcinoma cells compared with normal tissues, whereas anti-S100a9 Ab treatment suppressed their protein levels." (PMID 29326691, 2017).
corneal infection (3 papers, 2019 to 2024). A viral or bacterial infectious process affecting the cornea. "In our earlier study we investigated the expression of AMPs from corneal scrapings of patients with P. aeruginosa corneal infections and saw differential expression of several AMPs, including human β defensins (hBD) 2, and 3, S100A9, S100A12 and LL-37." (PMID 32507000, 2020). "We determined the expression pattern of AMPs elicited in corneal infections caused by S. pneumoniae in patients for the first time, and we found significantly increased expressions of hBD2 and 3, S100A8, S100A9, S100A12, LL-37, lipocalin, Rnase7, and hepcidin." (PMID 30845777, 2019).
dementia (3 papers, 2016 to 2024). Loss of intellectual abilities interfering with an individual's social and occupational functions. "Intriguingly, plaque enrichment in S100A9 was attributable to the accumulation of the deamidated variant of this protein, suggesting a critical role of protein deamidation in the pathology of dementia." (PMID 27809929, 2016).
esophageal adenocarcinoma (3 papers, 2014 to 2021). A malignant tumor with glandular differentiation arising predominantly from Barrett mucosa in the lower third of the esophagus. "Moreover, miR-196a levels were conversely correlated with long-term survival esophageal adenocarcinoma and regulated the role of pro- and anti-apoptotic functions by targeting keratin 5, small prolinerich protein 2C, and S100 calcium-binding protein A9." (PMID 32903213, 2020).
gastric tumors (3 papers, 2010 to 2024). "The increased expression of the PPARδ target gene, Agptl4, the TGFβ-activated genes Runx1 and Runx2, and S100A8 and S100A9 in the gastric tumors indeed suggests a duality of function of both PPARδ and TGFβ signaling in gastric tumorigenesis." (PMID 21318167, 2010). "Gene ontology analysis of gene expression in the gastric tumors indicates that PPARδ, MMP12, MMP13, Cxcl1, Cxcl5, S100A8, and S100A9 share both common and disparate pathway interactions that likely contributed to the tumorigenic phenotype." (PMID 21318167, 2010).
glaucoma (3 papers, 2024 to 2026). Increased pressure in the eyeball due to obstruction of the outflow of aqueous humor. "We found that circulating S100A9 levels were elevated in patients with glaucoma and positively associated with disease stage." (PMID 41080559, 2025). "In this study, we investigated the association between S100A9 and glaucoma by enrolling 121 patients with glaucoma, administering intravitreal injections of recombinant murine S100A9 (rmS100A9), and employing an elevated intraocular pressure (EIOP)-induced glaucoma mouse model." (PMID 41080559, 2025). "Retinal S100A9 expression was significantly elevated and correlated with progressive retinal ganglion cell (RGC) loss in EIOP glaucoma mice." (PMID 41080559, 2025). "These parallels suggest a potential role for S100A9 in glaucoma; however, its precise contribution remains unclear." (PMID 41080559, 2025). "Moreover, another study found elevated levels of S100A9 in the tears of glaucoma patients, indicating surface inflammatory biomarkers." (PMID 39125762, 2024). "Our study identified and validated six neuroinflammation-related hub genes in glaucoma (SERPINA3, LCN2, MMP3, S100A9, IL1RN, and HP)." (PMID 39125762, 2024). "S100A9 has also been reported to regulate TNFα production by activating the TLR4 pathway in acute herpetic neuralgia, a possible target for glaucoma therapy." (PMID 39125762, 2024).
Hepatic steatosis (3 papers, 2015 to 2022). Steatosis is a term used to denote lipid accumulation within hepatocytes. "Activating transcription factor 3 (ATF3)/S100A9 signalling plays an important role in GC‐mediated G‐MDSC accumulation in the fatty liver disease." (PMID 33094923, 2020). "The serum level of S100A9 was correlated with the NAFLD Activity Score and the severity of hepatic steatosis." (PMID 35790963, 2022). "There is a significant positive correlation between serum levels of S100A9 and NAFLD Activity Score (NAS), the severity of hepatic steatosis, and lobular inflammation (r = 0.80, 0.64 and 0.86, P < 0.001)." (PMID 25993652, 2015). "We found that serum levels of S100A9 positively correlated with NAS and histologic features of hepatic steatosis and lobular inflammation (r = 0.80, 0.64, and 0.84, respectively, P < 0.001), indicating that it is a reliable marker for the severity of hepatic histologic features." (PMID 25993652, 2015).
hypertriglyceridemia (3 papers, 2019 to 2025). A laboratory test result indicating elevated triglyceride concentration in the blood. "Treating ID mice with the protein S100A9 rescues the polarization and lipid-related changes caused by ID in the Kupffer cells, and, through them, rescues hypertriglyceridemia and hyperketonemia in a TLR4-dependent manner." (PMID 40874857, 2025). "Mice overexpressing S100A9 in the context of intact TRL4 (ie, ID;Tlr4WT;S100A9OE mice) had improved hypertriglyceridemia as compared to ID;Tlr4WT mice; however, this effect of S100A9 was blunted in the context of TRL4 deficiency (ie, ID;Tlr4KO;S100A9OE mice)." (PMID 40874857, 2025). "By affecting different immune niches in the liver and SkM, S100A9 rescues hypertriglyceridemia and hyperketonemia and stimulates SkM glucose uptake via Toll-like-receptor 4 (TLR4)-dependent mechanism." (PMID 40874857, 2025). "In conclusion, S100A9's ability to normalize hyperketonemia and hypertriglyceridemia in ID is primarily driven by TLR4 signaling in KCs, uncovering a novel mechanism for regulating metabolic dysfunction." (PMID 40874857, 2025). "The conclusion that TLR4 in the KCs mediates the ketone/lipid improving action of S100A9 is strongly supported by the fact that re-expression of TLR4 in KCs of ID mice is sufficient for virtually all of the hyperketonemia- and hypertriglyceridemia-lowering effect of S100A9." (PMID 40874857, 2025).
Kawasaki disease (3 papers, 2018 to 2024). A rare inflammatory disease characterized by an acute febrile, systemic, self-limiting, medium-vessel vasculitis primarily affecting children. "Consistent with our findings, a study reveals that CM highly express S100A8, S100A9, and S100A12, IM express HLA-DQA1 and HLA-DPA1 and NCM mainly express CD16, demonstrating a distinct transcriptome across monocyte subsets in Kawasaki disease." (PMID 39318997, 2024).
memory impairment (3 papers, 2010 to 2014). "In our study, we found that S100A9 is related with learning and memory impairment in the AD mice model." (PMID 24586443, 2014). "To confirm that the memory impairment in Tg2576 mice was actually improved by sh-S100a9 injection, we performed the probe test 48 h after the final trial and recorded the duration of time spent in zone 4 without the platform." (PMID 20098622, 2010).
oral squamous cell carcinoma (3 papers, 2021 to 2023). "The overexpression of S100A9 encoding calgranulin B has been suggested to play a vital role in the progress of oral squamous cell carcinoma (OSCC) and may serve as a diagnostic and prognostic biomarker for OSCC and nonsmall-cell lung carcinoma." (PMID 35574316, 2022). "CD59 has been evaluated as a salivary biomarker for oral squamous cell carcinomas together with M2BP, S100A9/MRP14, and catalase, achieving diagnostic sensitivity of 90%, specificity of 83%, and AUROCC of 0.93 for OSCC detection." (PMID 34359613, 2021). "Expression of S100A9 and S100A8 in brush biopsies was able to differentiate between normal mucosa from premalignant and oral squamous cell carcinoma cells." (PMID 37810966, 2023).
pancreatic adenocarcinoma (3 papers, 2014 to 2023). "In addition, based on data from colorectal and pancreatic adenocarcinoma cell lines, it has been shown that S100A9 is preponderant in the promotion of tumor growth in SMAD4-negative cancer cells supporting a link between S100A9/TGF-β/SMAD4." (PMID 34201758, 2021). "In line with our results, previous research has demonstrated significant overexpression (> 10-fold) of S100A8 in pancreatic adenocarcinoma, whereas S100A8 and S100A9 were rarely expressed in normal pancreatic tissue and tissue of chronic pancreatitis." (PMID 37280516, 2023).
pneumococcal pneumonia (3 papers, 2010 to 2023). A febrile disease caused by STREPTOCOCCUS PNEUMONIAE. "The current study was conducted to further characterize S100A9 in lung antibacterial immunity in a well-defined model of pneumococcal pneumonia in mice." (PMID 37467233, 2023). "Collectively, S100A9 controls central antibacterial immune mechanisms of the lung with essential relevance to survival of pneumococcal pneumonia." (PMID 37467233, 2023). "Collectively, our study supports the view that S100A9 is not critical for lung neutrophil recruitment during pneumococcal pneumonia." (PMID 37467233, 2023).
polycystic ovary syndrome (3 papers, 2021 to 2025). A disorder that manifests as multiple cysts on the ovaries. "In polycystic ovary syndrome (PCOS) patients, follicular fluid EVs are enriched in S100-A9, which promotes inflammation and disrupts steroidogenesis by activating the NF-κB pathway, thereby impairing granulosa cell function." (PMID 41358005, 2025).
promyelocytic leukemia (3 papers, 2012 to 2021). "In fact, human recombinant S100A9 were evaluated in vitro in chemotaxis assy for human promyelocytic leukemia (HL-60) cell line at concentrations varying from 32 to 1,024 ng/ml." (PMID 22962574, 2012). "In acute promyelocytic leukemia (APL), the FAB M3 AML subtype, S100A9 and A8 seem to be expressed less compared to other subtypes despite the promyelocytic phenotype of these blasts." (PMID 33801279, 2021).
streptococcal pneumonia (3 papers, 2013 to 2024). A febrile disease caused by streptococcus pneumoniae. "Blockade of S100a8 and S100a9 also suppresses neutrophil migration in response to lipopolysaccharide in the air pouch and monocyte/macrophage infiltration during streptococcal pneumonia." (PMID 29326691, 2017). "In line, in a mouse model of streptococcal pneumonia anti-S100A8 and anti-S100A9 caused neutrophil and macrophage recruitment to alveoli to diminish by 70–80%." (PMID 23874727, 2013).
thrombosis (3 papers, 2022 to 2024). "Strikingly, the blood of COVID‐19 patients with thrombosis contains high levels of circulating NETs, S100A8 and S100A9, along with an abundance of immature neutrophils in the bloodstream." (PMID 38319150, 2024).
vasculitis (3 papers, 2009 to 2017). "We analyzed the cohort of 138 RA patients for associations between serum levels of S100A9, S100A8, S100A12 and sRAGE with RA clinical variables, CV risk factors, and with complications such as vasculitis, radiographic changes, and CV events." (PMID 19284577, 2009). "Over the past 20 years, S100A8, S100A9 and their complexes have emerged as very potent biomarkers of a wide range of inflammatory processes, including rheumatoid arthritis, juvenile idiopathic arthritis, inflammatory bowel disease, acute lung inflammation and vasculitis." (PMID 22489132, 2012).
abscess (2 papers, 2023 to 2024). An inflammatory process characterized by the accumulation of pus within a newly formed tissue cavity which is the result of a bacterial, fungal, or parasitic infection or the presence of a foreign body. "To examine the protein levels of His107 methylated and total S100A9, we harvested local abscess-infiltrating cells, BM cells and spleen cells at different time points during S. aureus infection." (PMID 37522633, 2024). "Given that it was not feasible to obtain abscess tissue at day 0, we mainly evaluated His107 methylation of S100A9 at the acute stage (day 2) and the resolving stage (days 8–10) of infection." (PMID 37522633, 2024).
adenoma (2 papers, 2019 to 2021). A neoplasm arising from the epithelium. "In the advanced adenoma group, differences between the healthy mucosa and adenomatous tissue were found in S100A6 (p = 0.002), S100A8 (p = 0.002), S100A9 (p = 0.021) and S100A11 (p = 0.029)." (PMID 33466593, 2021). "Differences in the mRNA for S100A4 in the non-advanced adenoma group and the mRNA for S100A9 and S100A11 in the advanced adenoma group between men and women were confirmed." (PMID 33466593, 2021).
allergic contact dermatitis (2 papers, 2014 to 2023). An inflammatory skin condition caused by an immune response to direct contact between the skin and an allergen. "It showed that sustained exposure of S100A8/S100A9 hindered the differentiation and antigen presentation capacity of DCs, thereby leading to attenuated T cell response in allergic contact dermatitis." (PMID 37337301, 2023). "Here, using optical molecular imaging, we demonstrate that the alarmin S100A8/S100A9 serves as a sensitive local and systemic marker for the detection of even sub-clinical disease activity in inflammatory and immunological processes like irritative and allergic contact dermatitis." (PMID 25098555, 2014).
ANCA)–associated vasculitis (2 papers, 2018 to 2022). "In patients with active antineutrophil cytoplasm antibody (ANCA)–associated vasculitis (AAV), renal biopsies demonstrate glomerular infiltration of S100A8/S100A9-positive immune." (PMID 36017003, 2022).
aneurysm (2 papers, 2023 to 2024). Bulging or ballooning in an area of an artery secondary to arterial wall weakening. "Aneurysm is a significant vascular disease whose development is also associated with S100A9." (PMID 38504474, 2024). "S100A9 is not only a marker for the diagnosis and differentiation of aneurysms, but also an important substance for predicting the prognosis of aneurysms." (PMID 38504474, 2024). "However, whether S100A9 serves as a target for the treatment of aneurysms and aortic dissection remains to be further investigated." (PMID 38504474, 2024). "These demonstrate that S100A9 may be a marker for predicting the prognosis of aneurysms." (PMID 38504474, 2024).
Anxiety (2 papers, 2019 to 2021). Intense feelings of nervousness, tension, or panic often arise in response to interpersonal stresses. "T-lymphocyte expression of S100a8 and S100a9 showed a similar positive correlation with anxiety-like behavior, but also positively correlated with the corner zone ratio of the social interaction test." (PMID 31139062, 2019). "It will therefore be important to assess the effect of S100A9 inhibition on DSS-induced stress and anxiety." (PMID 34758843, 2021). "Stress-induced upregulation of S100A8 and S100A9 has also been reported previously in mouse hippocampus, though it is unclear if S100A8/A9 expression in the CNS is beneficial or detrimental to stress and anxiety." (PMID 34758843, 2021).
arteriosclerosis (2 papers, 2023 to 2024). A vascular disorder characterized by thickening and hardening of the walls of the arteries. "GeneChip analysis revealed increased six key genes during the process of arteriosclerosis including Apol11b, Camp, Chil3, S100a8, S100a9, and Spta1." (PMID 36982506, 2023).
arthropathy (2 papers, 2022 to 2024). Any disorder of the joints. "The median levels of S100A9 was 47 pg/mL (IQR 30-113) in ALL with arthropathy versus 511 pg/mL (IQR 315-1281) in JIA, p < 0.001." (PMID 36096831, 2022).
brain injury (2 papers, 2014 to 2021). Acute and chronic (see also brain INJURIES, CHRONIC) injuries to the brain, including the cerebral hemispheres, CEREBELLUM, and brain STEM. "In traumatic brain injury (TBI) S100A9 itself rapidly forms amyloid plaques, which were reactive with oligomer-specific antibodies, but not with Aβ and amyloid fibrillar antibodies." (PMID 24240735, 2014). "In addition, a recent study demonstrated that genetic deletion of S100A9 had a neuroprotective effect, which indicates that S100A9 may be a potential treatment target for brain trauma." (PMID 33504361, 2021).
calculus (2 papers, 2021 to 2024). "Among the 20 common stone matrix proteins, S100A8 and S100A9 were the most frequently detected and they appeared in all kinds of urinary stones." (PMID 34395096, 2021).
Candida infection (2 papers, 2020 to 2021). "For instance, S100A9 alarmins can be produced from the vaginal epithelium in response to Candida infection." (PMID 34282934, 2021). "Previous studies have identified the alarmins, S100A8 and S100A9, as key chemotactic mediators of the acute PMN response toward Candida infection." (PMID 33262741, 2020).
cervical squamous cell carcinoma (2 papers, 2014 to 2021). A squamous cell carcinoma arising from the cervical epithelium. "Overexpressed S100A9 decreased cisplatin sensitivity and apoptosis rate in squamous cervical cancer cells." (PMID 34249502, 2021). "Decreased expressions of S100A9 and S100A8 were observed in human cervical squamous cell carcinoma." (PMID 25298751, 2014).
Chronic colitis (2 papers, 2015 to 2025). A chronic inflammatory disease of the large intestine (colon, cecum and rectum). "Here we demonstrate that the dynamic process of the neoplastic progression of IECs in chronic colitis is regulated by the increased production of CHI3L1, which reciprocally regulates the expression of S100A9 under inflammatory conditions." (PMID 26431492, 2015).
chronic hepatitis B (2 papers, 2018 to 2023). "Here, we evaluated the relationship of serum S100A9 with viral replication and liver necroinflammation in patients with chronic hepatitis B (CHB) infection." (PMID 29615081, 2018). "S100A8 and S100A9 levels were analyzed in plasma of 187 transplant-free HBV-ACLF patients, 28 healthy controls and 40 chronic hepatitis B (CHB) patients." (PMID 37469934, 2023).
chronic lung disease (2 papers, 2015 to 2025). According to the definitions of the American and British Thoracic Societies, including pulmonary functional tests, X-rays, and CT scans for items such as fibrosis, bronchiectasis, bullae, emphysema, nodular or lymphomatous abnormalities. "MMP8 contributes to tissue remodeling in chronic lung diseases, while S100A9, a calcium-binding protein, amplifies neutrophilic inflammation." (PMID 41044788, 2025). "Antimicrobial S100-A9 (calgranulin B) dimerizes with S100A8 (calgranulin A) and this acts as a signal for neutrophil and lymphocyte recruitment, and in human studies it has been speculated that this could be a biomarker for disease severity in chronic lung diseases." (PMID 26067998, 2015).
cognitive decline (2 papers, 2020 to 2022). "Similarly, disease associated microglia (DAM) cells, assumed to have a protective function, have low S100a8 and S100a9 levels; while granulocytes/neutrophils have high S100a8 and S100a9 expression and may promote AD-like pathology and cognitive decline." (PMID 32469975, 2020). "Neutralizing each of these targets (Aβ, RAGE, S100A9, and TLR4) individually has been shown to slow cognitive decline in animal models." (PMID 36291595, 2022). "Aβ, RAGE, S100A9, and TLR4 play important roles in AD pathogenesis by orchestrating the feed-forward mechanism between neuroinflammation and neurodegeneration, two pathways driving the cognitive decline in AD." (PMID 36291595, 2022).
colorectal adenoma (2 papers, 2012 to 2016). An adenoma that arises from the colon or rectum. "Plasma levels of S100A8 and S100A9 increase appreciably in patients with colorectal adenomas and established CRCs." (PMID 23166536, 2012).
cyst (2 papers, 2013 to 2020). A sac-like closed membranous structure that may be empty or contain fluid or amorphous material. "S100A8 with S100A9 complex is believed to facilitate the cyst migration in PCOS condition." (PMID 32478041, 2020).